IGF1R (insulin like growth factor 1 receptor)
Diseases named in the same sentence as IGF1R in open-access papers (continued):
Sharing a sentence is not in itself a finding about the gene and the disease.
osteosarcoma (continued). "IGF-1R inhibition with monoclonal antibodies resulted in growth retardation and prolonged event-free survival in osteosarcoma-bearing mice." (PMID 22577336, 2012). "Some osteosarcoma cell lines express that functional insulin-like growth factor 1 receptor (IGF-1R) on their cell surface that, in turn, stimulates proliferation." (PMID 22577336, 2012). "In some in vivo models of Ewing sarcoma and osteosarcoma targeting IGF-1R with CP751871 dramatically suppressed VEGF transcription and reduced tumor-associated VEGF within 24 hours of antibody administration." (PMID 21197468, 2011). "Targeting IGF-1R with specific inhibitors has shown promise in preclinical studies, suggesting that it may serve as a viable therapeutic target in osteosarcoma treatment." (PMID 40283955, 2025). "Treatment with an anti-IGF1R antibody in mouse xenografts of osteosarcoma showed promising results, and this preclinical evaluation provided motivation for a phase II clinical trial testing an anti-IGF1R antibody in combination with mTOR inhibitor in several sarcomas." (PMID 35887382, 2022). "In combination with these previous findings, our results suggest that IGF1R expression is amplified in a subset of osteosarcoma due to increased IGF1R copy number, and that both can successfully stratify patients into high- and low-risk groups independent of initial metastatic status." (PMID 35887382, 2022). "Likewise, there is prominent downregulation of miR-let-7b in osteosarcoma cell lines and tissues, and results conveyed its antitumor effects via interaction with IGF1R and inhibiting IGF1R expression." (PMID 35831411, 2022). "Considered the relationship between miR‐433‐3p and IGF1R, we proposed the hypothesis that circ_0002137 regulated the progression of osteosarcoma through sponging miR‐433‐3p/IGF1R." (PMID 33621401, 2022). "Though single-agent therapies against IGF-1R or mTOR have proved ineffective in osteosarcoma, the ability to co-target these pathways using novel biologically-targeted agents would be expected to yield synergistic anti-cancer activity, as has been observed in preclinical bone sarcoma models." (PMID 35284040, 2022). "Moreover, the IGF-1R protein level was considerably higher in osteosarcoma tumors (P < 0.0001), Ewing sarcoma tumors (P < 0.0001) and GCT (P < 0.01) compared to their matched noncancerous tumor margins, respectively." (PMID 36713521, 2022). "In addition to IGF2BP1, let-7b targets a variety of oncogenes and has been proposed to act as a tumor suppressor in human osteosarcoma by targeting insulin-like growth factor-1 receptor." (PMID 33937369, 2021). "This investigation highlighted also that miR-302a suppressed osteosarcoma metastases through targeting IGF1R, and this may provide a novel target to prevent metastasis in osteosarcoma patients." (PMID 34484116, 2021). "Interestingly, all these studies have reported only downregulation of specific miRNAs which lead to an increased expression of IGF1R in osteosarcoma." (PMID 34484116, 2021). "Similarly, a direct correlation was observed between Cyr61 and IGF1R expression in osteosarcoma tissues analyzed by immunohistochemistry." (PMID 34440844, 2021). "Interestingly, overexpression of IGF1R also has been shown in canine osteosarcoma and to strongly correlate with tumour stage and adverse outcome." (PMID 33295144, 2021). "Furthermore, the investigators performed studies on immunodeficient mice indicating that aggressive in vivo behavior (tumorigenesis and occurrence of metastasis) of canine osteosarcoma cells positively correlates with the expression of IGF1-R." (PMID 33807419, 2021). "As reported in the following lines, it is noteworthy that the majority of the studies available in the Literature concerning miRNAs, the GH/IGF1 axis and the IGF system in osteosarcoma are focused on miRNAs that target, both directly or indirectly, the IGF1R both in vivo and in vitro." (PMID 34484116, 2021).
osteosarcoma (continued). "The identification of the lncRNA SNHG12/miR-195-5p/IGF1R axis underlines the importance of lncRNA SNHG12 in the regulation of tumor progression, and could an interesting way to inhibit osteosarcoma progression and metastases." (PMID 34484116, 2021). "However, the results of clinical trials evaluating those agents as monotherapy were disappointing, as only 3/60 (5%) cases of osteosarcoma treated with the anti-IGF1R mAb robatumumab showed complete or partial response." (PMID 34440844, 2021). "The expression of IGF-1R is closely related to distant metastasis and prognosis of osteosarcoma." (PMID 32984034, 2020). "For example, mutations in genes involved in IGF (insulin-like growth factor) signalling, including the IGF1 receptor (IGF1R), were identified in around 7–14% of osteosarcomas, with many of these genes having altered activity compared with normal human osteoblasts or mesenchymal stem cells." (PMID 31741049, 2020). "However, clinical trials demonstrate that only a small subset of osteosarcoma patients respond to IGF-1R antibodies." (PMID 26563243, 2016). "Finally, PDGFRα, Axl, PDGFRβ, RYK, EGFR, EphA2, EphA10 and IGF1-R are key targets of imatinib mesylate in osteosarcoma." (PMID 24599309, 2014). "Of the 21 osteosarcoma cases with elevated miR-194, 15 (71.4%) had low levels of IGF1R." (PMID 25096247, 2014). "Clinical data using dual IGF1R/IR inhibitors osteosarcoma is still very limited." (PMID 23688189, 2013). "We characterized overexpression of the insulin-like growth factor receptor (IGF1R) signaling pathways in human osteosarcoma as compared with osteoblasts and with the hypothesized progenitor cells of osteosarcoma – mesenchymal stem cells." (PMID 23688189, 2013). "We specifically chose to treat osteosarcoma cells with a dual inhibitor, because the insulin receptor can activate the same downstream signaling pathways as IGF1R, therefore providing cells a way to circumvent single inhibition of IGF1R." (PMID 23688189, 2013). "An inhibition of intrinsic IRS-1 phosphorylation at Y612 was detected after treatment with OSI-906 in all cell lines, indicating that this inhibitor could affect signaling downstream IGF1R in osteosarcoma cells." (PMID 23688189, 2013). "It is therefore possible that inhibiting these pathways with a dual IR/IGF1R kinase inhibitor, such as OSI-906, may reduce tumor sizes, as well as osteosarcoma metastasis, the leading cause of death in these patients." (PMID 23688189, 2013). "IGFBP4 and GAS6, which code for proteins that inhibit IGF1R signaling, showed the highest significant downregulation (log fold changes <−4) in a four-way analysis, in which osteosarcoma pretreatment biopsies or cell lines were compared with osteoblastic cultures (n=3) or MSCs (n=12)." (PMID 23688189, 2013). "However, less is known about the impact of nuclear or phosphorylated IGF-1R in osteosarcoma." (PMID 35284040, 2022). "Interestingly, although increased pIGF-1R nuclear staining was associated with subtypes other than high-grade bone, IGF-1R nuclear staining intensity did not correlate with osteosarcoma subtype, possibly due to low sample sizes." (PMID 35284040, 2022). "Indeed, these results suggest that IGF-1R or downstream signaling proteins may be attractive targets for therapy in osteosarcoma." (PMID 35284040, 2022).
osteosarcoma (continued). "Moreover, the effect of exogenous biglycan on the activation of IGF-1R and the mediatory role of β-catenin hypothesize the plausible effect of β-catenin/IGF-1R signaling pathway in controlling the osteosarcoma cell growth." (PMID 36713521, 2022). "Furthermore, cisplatin-resistant osteosarcoma cells characterised by elevated basal activation of IGF-1R/AKT display hypersensitivity to nutlin-3a but reduced AKT-dependent autophagy flux, and inhibiting IGF-1R, AKT or autophagy flux improved the nutlin-3a response." (PMID 34911439, 2021). "The authors showed also that miR-939 overexpression downregulated PI3K-AKT pathway downstream the IGF1R and the restoration of miR-939 could represent a potential therapeutic approach for patients with osteosarcoma following the purpose of a miRNA-based targeted anticancer therapy." (PMID 34484116, 2021). "Similarly, miR-let-7b was shown to be significantly downregulated in osteosarcoma tissues and cell lines and the functional studies revealed that the antitumor effect of miR-let-7b was probably due to targeting and suppressing Insulin Like Growth Factor 1 Receptor (IGF1R) expression." (PMID 34122072, 2021). "Both sorafenib and IGF1R inhibitors were tested because the focus of osteosarcoma research has shifted towards gaining a better understanding of the driving forces behind tumor development and progression and then hypothesis-driven drug discovery and development." (PMID 27990273, 2016). "Moreover, IGF1R play important roles in tumor growth and metastasis of osteosarcoma." (PMID 24391788, 2013). "Osteosarcoma tissues exhibit overexpression of SNHG12, which then leads to an increase in the tumorigenesis and metastasis induced by Notch2-and insulin-like growth factor 1 receptor (IGF1R) through the regulation of miR-195-5p." (PMID 38028627, 2023). "Currently, potential effective targets for CAR-T cell therapy in osteosarcoma include HER2, IGF1R, ROR1, EphA2, CSPG4, folate receptor with EC17, B7-H3, GD2, NKG2D, ALCAM/CD166, IL-11Rα, and FAP." (PMID 38187386, 2023). "In this study, we demonstrated a correlation between nuclear IGF-1R and the Hippo pathway effectors, YAP and TAZ staining in human osteosarcoma." (PMID 35284040, 2022). "Evidence revealed that IGF-1R downstream signaling through MEK/ERK pathway and Akt activation mediates migration and invasion of osteosarcoma cells." (PMID 36713521, 2022). "Cixutumumab, ganitumab, robatumumab, and figitumumab, targeting the insulin-like growth factor-1 receptor (IGF1R), have been tested in advanced RMS, EWS, and osteosarcoma." (PMID 34804076, 2021). "Targeting the Insulin-Like Growth Factor-1 Receptor (IGF-1R), a protein involved in the pathogenesis of bone and soft tissue sarcomas, is another strategy explored in osteosarcoma trials." (PMID 33917001, 2021). "For example, miRNA16, which negatively regulates IGF1R/Kras/Raf1/MEK/ERK pathway and cell proliferation, is downregulated in osteosarcoma compared to normal controls." (PMID 34440844, 2021). "For example, SRC kinase, which plays a key role in the development of osteosarcoma, can be activated, respectively by VEGFRs, KIT, RET, PDGFRs, IGF-1R, and AXL." (PMID 32984034, 2020). "Anti-IGF1R CAR T cells and anti-ROR1 CAR T cells generated from a sarcoma patient were able to significantly reduce tumour growth in osteosarcoma xenograft mice models." (PMID 33207697, 2020). "Expression of IGF receptor 1 (IGF1R), IGF-1, and IGF-2 have been reported in osteosarcoma cell lines and patient samples, further suggesting its role in osteosarcoma pathogenesis." (PMID 32961800, 2020). "In addition, this study found that AG1024 had synergistic effects with doxorubicin even in the doxorubicin-resistant variant of the 143B cell line and increased doxorubicin sensitivity in this cell line, suggesting that inhibiting IGF-1R may be useful in treating resistant osteosarcoma." (PMID 32961800, 2020).
osteosarcoma (continued). "In osteosarcoma, NNT-AS1 can sponge miR-320a and up-regulate the expression of β-catenin, RUNX2, p-AKT, insulin-like growth factor type 1 receptor (IGF1R), MYC, cyclin D1, and MMP-13, thereby promoting osteosarcoma cell growth and tumor development." (PMID 33113895, 2020). "We validate this observation using fluorescence in situ hybridization (FISH) in an additional 87 osteosarcomas, with IGF1 receptor (IGF1R) amplification observed in 14% of tumours." (PMID 28643781, 2017). "In osteosarcoma, overexpression of miR-194 inhibits tumor growth and metastatic potential via the regulation of CDH2 and IGF1R." (PMID 26909612, 2016). "Another study pointed out that IGF1R (14.6-up-regulated in CEM/ADR5000 cells) enhanced the cytotoxicity of doxorubicin in both sensitive and resistant osteosarcoma cells." (PMID 27824156, 2016). "For instance, miR-16 inhibits cell proliferation by targeting IGF1R and the Raf1-MEK1/2-ERK1/2 pathway in osteosarcoma, and miR-802 promotes osteosarcoma cell proliferation by down-regulating the p27 cell-cycle inhibitor." (PMID 26913720, 2016). "The adoptive transfer of IGF1R and ROR1 CAR T cells derived from a sarcoma patient significantly reduced tumor growth in pre-established, systemically disseminated and localized osteosarcoma xenograft models in NSG mice." (PMID 26173023, 2015). "Osteosarcoma xenograft models OS1, OS17, and OS31 were treated with monotherapy anti-IGF1R therapies SCH 717454, BMS 754807, and IMC A12 in previous PPTP studies." (PMID 25170759, 2014). "Several kinases such as IGF-1R, PI3K/AKT, PDGFR, mTOR and Src have been found to be highly expressed in different osteosarcomas, particularly in the late stage of the development of drug resistant tumor." (PMID 25236161, 2014). "These indicate that miR-133b play a role as a tumor suppressor gene in osteosarcoma through inhibiting PI3K/Akt signaling and down-regulating several anti-apoptotic molecules and oncogenes such as BCL2L2, MCL-1, IGF1R, MET, and FAK." (PMID 24391788, 2013). "Further, to better understand the mechanisms how miR-133b regulates cellular phenotypes of osteosarcoma cells, we first measured the expression of BCL2L2, MCL-1, IGF1R and MET, which are identified as the target genes of miR-133b in several cancers." (PMID 24391788, 2013). "The western blotting results showed that over-expression of miR-133b decreased the expression of BCL2L2, MCL-1, IGF1R and MET in osteosarcoma cells U2-OS and MG-63." (PMID 24391788, 2013). "Results showed that expression of BCL2L2, MCL-1, IGF1R, MET, phospho-Akt and FAK were significantly decreased in miR-133b over-expressed osteosarcoma cell lines U2-OS and MG-63." (PMID 24391788, 2013). "Over-expression of miR-133b in osteosarcoma cell lines U2-OS and MG-63 decreases the expression of BCL2L2, MCL-1, IGF1R, MET and FAK, leading to the inactivation of Akt." (PMID 24391788, 2013). "Although these findings differ from some other investigations, a similar PPP-induced downregulation of both IGF-1R/AKT and their phosphorylated forms has been shown in a multi-drug resistant osteosarcoma cell line." (PMID 22159423, 2012). "Inhibitors of receptor tyrosine kinases, including insulin-like growth factor 1 receptor (IGF-1R) and a platelet-derived growth factor receptor (PDGFR) have been investigated and developed for osteosarcoma treatment." (PMID 18782081, 2008). "However, clinical trials in osteosarcoma have shown that single‐target therapy, such as inhibiting VEGFs (with bevacizumab), KIT and PDGFRα (with imatinib), or IGF‐1R (with cixutumumab or R1507) has limited efficacy." (PMID 40344484, 2025). "The IGF-1R protein level was significantly increased in high-grade, metastatic and recurrent osteosarcoma tumors compared to low-grade (P=0.01), non-metastatic (P=0.002) and non-recurrent tumors (0.008)." (PMID 36713521, 2022).
osteosarcoma (continued). "In addition, expression of the IGF1R, IGF1 and IGF2 was detected in most osteosarcoma cell lines and patient-derived tissues." (PMID 34440844, 2021). "IGF1R was a predicted target of miR-497, and the authors showed that IGF1R negatively correlated with miR-497 and correlated positively with AFAP-AS1 expression in osteosarcoma tissues." (PMID 34484116, 2021). "This should not be the cases if the IGF1R gene alteration represents the oncogenic driver itself as suggested in the osteosarcomas presented here." (PMID 33295144, 2021). "A clinical trial (NCT00617890) evaluating the efficacy of an IGF1R antibody (Robatumumab) on bone sarcomas, including osteosarcomas, has already been carried out without any evidence of clinical benefit." (PMID 33295144, 2021). "In vitro, miR-503 was also lower in osteosarcoma cells than that in normal osteoblasts cells, and overexpression of miR-503 suppressed the proliferation and invasion of osteosarcoma U2OS cells, thus, it acted as a tumor suppressor in osteosarcoma via inhibiting its target, IGF-1R." (PMID 33762949, 2021). "However, clinical trials in osteosarcoma have demonstrated the low efficacy of single-target therapy by inhibiting VEGFs (by bevacizumab), KIT and PDGFRα (by imatinib), and IGF-1R (by cixutumumab or R1507)." (PMID 32984034, 2020). "The receptor tyrosine kinases (RTKs) MET, IGF-1R, AXL, PDGFRs, KIT, and FGFRs might be relevant but unimportant targets for osteosarcoma treatment." (PMID 32984034, 2020). "In another phase II trial of the IGF-1R antibody cixutumumab in children with osteosarcoma, no PRs were observed in 11 patients." (PMID 32984034, 2020). "The receptors MET, IGF-1R, AXL, PDGFRs, KIT, and FGFRs might be relevant but unimportant RTKs for osteosarcoma." (PMID 32984034, 2020). "In osteosarcoma, increased levels of IGF-1 and IGF-1R have been found that seem to lead to tumor progression through transformation, proliferation, decreased susceptibility to apoptosis, and a phenotype prone to metastasis, including increase cell motility, invasion, and angiogenesis." (PMID 30881341, 2019). "In this perspective, we emphasize the current advances and interactions involving the insulin/IGF1R, SIRT1, and FOXOs pathways in the bone and osteosarcoma for a better understanding of the mechanisms potentially underpinning tissue degeneration and tumorigenesis." (PMID 30881341, 2019). "Indeed, it was shown in osteosarcoma cells that dual inhibition of IGF-1R and insulin receptor is more effective than IGF-1R inhibition alone." (PMID 26563243, 2016). "The current paper emphasizes that the IGF pathway plays an important role in osteosarcoma pathogenesis, which is supported by other preclinical studies showing reduced proliferation in the majority of osteosarcoma cell lines and xenografts upon IGF 1 receptor (IGF-1R) inhibition." (PMID 26563243, 2016). "Overexpression of miR-194 inhibited tumor growth and metastasis of osteosarcoma probably by downregulating CDH2 and IGF1R. miR-194 may prove to be a promising therapeutic agent for osteosarcoma." (PMID 25096247, 2014). "To visualize mRNA expression of the IGF1R signaling pathway members, we used Ingenuity Pathways Analysis on LIMMA toptables from osteosarcoma cells as compared with mesenchymal stem cells and from osteosarcoma cells as compared with osteoblasts." (PMID 23688189, 2013). "In different human osteosarcoma cell lines an inhibition of the IGF-1- and -2-stimulated uptake of thymidine as well as a partial inhibition of the basal DNA synthesis was observed when the IGF-1R was blocked by monoclonal antibody α-IR3." (PMID 12618883, 2003).